TNF (tumor necrosis factor)
Diseases named in the same sentence as TNF in open-access papers (continued):
Sharing a sentence is not in itself a finding about the gene and the disease.
demyelination (20 papers, 2005 to 2025). "The pathophysiology of a variety of neurological disorders, including MS, is associated with TNF-α, a master pro-inflammatory product of activated microglia and peripheral macrophages implicated in the pathogenesis of CNS demyelination." (PMID 29803222, 2018). "CD8+ CTLs in the CNS produce and release several pro-inflammatory cytokines including interferon-γ (IFNγ) and tumor necrosis factor-α (TNF-α), which is proposed to result in substantial bystander destruction of resident CNS tissue and neural cells associated with demyelination." (PMID 37622115, 2023). "TNF-α is linked to the development of abnormal blood-nerve barrier permeability, monocyte recruitment or residential macrophage activation, and coordination of these inflammatory events with demyelination." (PMID 23469058, 2013). "Besides those with a family history of CNS demyelination, patients with familial occurrence of systemic autoimmune diseases (as our first case) might also be at increased risk of CNS demyelination with anti-TNF-α treatment." (PMID 28337644, 2017). "Evidence has shown that increased TNF-α expression spontaneously develops chronic inflammatory demyelination with 100% penetrance." (PMID 38213956, 2024). "Previous studies demonstrated that a substantial number of A1 astrocytes were activated in CPZ-induced demyelination lesions, and the A1 phenotype was mainly triggered by C1q, TNF-α, and IL-1α derived from microglia." (PMID 36092158, 2022). "Astrocytes secrete various inflammatory factors which have a critical role in demyelination diseases, including tumor necrosis factor-α (TNF-α), IL-1β, and interferon-γ (IFN-γ)." (PMID 35743941, 2022). "In the current study, we confirmed that inhibition of TRPV4 activity with RN-1734 suppressed microglial and astrocytic activation and decreased the production of IL-1β and TNF-α in mice with CPZ-induced demyelination." (PMID 30455633, 2018). "Antioxidant, shown to reduce interleukin-1 beta and tumor necrosis factor alpha in preclinical demyelination models." (PMID 30405407, 2018). "Anti-TNF-α treatment was discontinued as soon as demyelination was suspected and steroids were administered intravenously with consequent clinical improvement." (PMID 28337644, 2017). "It has been shown that in the CNS both CD4+ and CD8+ T cells are involved in the development of demyelination as a result of production by these cells of pro-inflammatory cytokines IFN-γ and TNF-α." (PMID 37153635, 2023). "Despite the potential biological role of TNF-α blockers in triggering or aggravating demyelination, infliximab may be another treatment option in refractory ICI-related demyelination." (PMID 33362680, 2020). "Two out of 77 patients had MRI lesions and 4 developed demyelination, but the overall rate of neurologic adverse events was comparable with the group of patients who had not received anti TNF -α blockers [92••]." (PMID 28337644, 2017). "With the aim of interpreting the opposing neurotoxic and neuroprotective effects of the TNF cytokine system described in the literature, we studied the effects of neuronal TNFR1 and TNFR2 using two CNS demyelination models in mice, EAE and CPZ-induced demyelination." (PMID 34565380, 2021).
Ewing sarcoma (20 papers, 2007 to 2025). A small round cell tumor that lacks morphologic, immunohistochemical, and electron microscopic evidence of neuroectodermal differentiation. "In keeping with this hypothesis, we found that OPG, which acts as a decoy receptor for RANK, inhibited RANKL-induced osteoclast formation and that an antibody to TNF-α inhibited osteoclast formation associated with the production of a soluble factor by Ewing's sarcoma cells." (PMID 17533390, 2007). "Combination NOA2 and PILRα blockade in vitro potentially reverses the inhibitory CD99:PILRα pathway linking Ewing sarcoma cells and macrophages, leading to restoration of TNF-α secretion." (PMID 38534214, 2024). "For example, in TNF-α treated Ewing's sarcoma cells, NF-κB activation increased both thioredoxin and MnSOD levels." (PMID 35841628, 2022). "Our findings are supported by the recent observation of the effect of TNFα on LC3 processing in Ewing sarcoma cells, MCF-7 cells and human skeletal muscle cells." (PMID 22417670, 2012). "It was alsodemonstrated that NF-κB-suppressed Ewing sarcoma cells stimulated with TNFα exhibit autophagy." (PMID 18566685, 2008). "Cultures of Ewing's sarcoma TAMs incubated on dentine slices for 21 days in the presence of M-CSF/RANKL or TNF-α/IL-1α showed a functional evidence of osteoclast differentiation with the formation of several areas of lacunar resorption on all dentine slices." (PMID 17533390, 2007). "With the knowledge that human macrophages express PILRα and confirmation that human PILRα binds human CD99, we next sought to evaluate the effects of blocking the macrophage PILRα:CD99 Ewing sarcoma binding axis on macrophage activity using TNF-α secretion as a proxy." (PMID 38534214, 2024). "Receptor activator for nuclear factor-κB ligand-independent mechanisms of osteoclast formation also exist in which cytokines, such as tumour necrosis factor (TNF)-α, a known product of Ewing's sarcoma tumour cells, can substitute for RANKL and induce osteoclast formation from circulating precursors." (PMID 17533390, 2007). "As Ewing's sarcoma cells are known to produce abundant TNF-α, we further investigated whether this cytokine played a role in stimulating osteoclast formation by tumour cells." (PMID 17533390, 2007). "Although TNFα can directly induce OC formation from TAMs in Ewing’s sarcoma in the presence of M-CSF, it is unknown if TNFα- induced OCs from TAMs have any difference with those from normal macrophages, because TNFα induces RANKL-independent OC formation from normal macrophages." (PMID 35011694, 2021). "However, the activity of TNFα in Ewing’s sarcoma is controversial." (PMID 34327193, 2021). "In studies on Ewing Sarcoma, the activation of CD99 in macrophages was shown to induce the secretion of characteristic chemokines such as IL1β, IL6, TNFα, and markers CD80 and CD86 by M1 macrophages." (PMID 41000385, 2025). "TNF-α is known to play a role in cell proliferation, and serum levels of TNF-α as well as M-CSF have been correlated with the progression of Ewing's sarcoma." (PMID 17533390, 2007). "Co-incubation of 14.G2a-28ζ transduced T cells with the GD2-positive Ewing sarcoma cell lines TC-71 and VH-64, but not the GD2-negative rhabdomyosarcoma cell line A-204 induced production of IFN-γ and TNF-α." (PMID 22374462, 2012). "When Ewing's sarcoma cells were cultured directly on bone (both in the presence and absence of M-CSF and RANKL or TNF-α), these cells did not differentiate into osteoclasts and were not capable of lacunar resorption." (PMID 17533390, 2007). "As TNF-α is known to stimulate RANKL expression and as TC71 Ewing's sarcoma cells expressed RANKL, it was not possible to determine if TNF-α in the TC71 conditioned medium was directly inducing osteoclastogenesis." (PMID 17533390, 2007).
H1N1 virus infection (20 papers, 2009 to 2025). "Another study in critically ill patients with ARDS caused by 2009 H1N1 virus infection has shown that the hallmarks of disease severity were elevated levels of IL-6, IL-15, IL-8 and TNF-α." (PMID 22235288, 2012). "In terms of mRNA expression, the expression of TNF-α and IL- 6 increases up to an alarming 100-fold and 150-fold after H1N1 virus infection, and the excessive inflammatory factors cause inflammatory damage to human respiratory tissues, resulting in discomfort such as sore throat and dry cough." (PMID 38426086, 2024). "Furthermore, the KEGG analysis revealed that multiple signaling pathways associated with the treatment of H1N1 influenza, including the NF-kappa B signaling pathway, the TNF signaling pathway, and additional pathways related to apoptosis, were implicated in moxa smoke." (PMID 41385483, 2025). "Therefore, this study suggests that the protective effect of hUCMSC-EVs against lung damage caused by influenza A virus (H1N1) infection may be related to the reduction in inflammatory cytokine levels of TNF-α, IL-1β, and IL-6, thereby alleviating pulmonary inflammation." (PMID 41009408, 2025). "Pyrogallol treatment reduced the increased levels of proinflammatory mediators (IL‐6, IL‐8, IP‐10, MCP‐1, RANTES, and TNF‐α) induced by H1N1 virus infection." (PMID 38617435, 2024). "Meanwhile, our results showed that the increased production of pro-inflammatory mediators (IL-6 and TNF-α) triggered by H1N1 virus infection was significantly decreased in A549 cells with h-PGDS overexpression." (PMID 37891648, 2023). "It has been reported that pregnant women infected with H1N1 influenza had significantly higher serum levels of IL‐6, IL‐10 and TNF‐α than healthy pregnant women, and IL‐6 was correlated with the severity of the disease." (PMID 37638092, 2023). "In mouse model of H1N1 influenza, peramivir inhibits the levels of TNF-α, IL6 and IFN-γ in the lung tissue." (PMID 35296098, 2022). "Kakkonto also reduces the expression of pro-inflammatory cytokines, including interleukin (IL)-1α, IL-6, and tumor necrosis factor (TNF)-α in H1N1 influenza-infected mice." (PMID 34531740, 2021). "The H7N9, H7N7 and H5N1 infected mouse lung transcriptome also showed higher levels of CXCL13, IL-6, IFNG, IFNB1, IRF9, IRF1, and TNF compared with 2009 pandemic H1N1 virus infections." (PMID 28558796, 2017). "The TNF gene was associated with disease severity, whereas IL1B and IL6 SNPs were associated with influenza A (H1N1) virus infection." (PMID 26657940, 2015). "In particular, IL-6 and TNF-α are the primary contributors to hypercytokinemia and were significantly increased following 2009 H1N1 virus infection." (PMID 22952892, 2012). "In our critically ill patients with nvA(H1N1) virus infection we found increased levels of some cytokines: IP-10, TNFα, IL-15, IL-12, IL-6, IL-8 and IL-9." (PMID 21062445, 2010). "In our critically ill patients with novel influenza A(H1N1) virus infection, the hallmarks of the severity of disease were IL-6, IL-15, IL-8 and TNFα." (PMID 21062445, 2010). "Our data show that TNF-α, IL- 6 and iNOS are increased to varying degrees in HEP-2 cells after H1N1 virus infection." (PMID 38426086, 2024). "Likewise, TARS1 is secreted from vascular endothelial cells in response to tumor necrosis factor (TNF)-α and sculpts a T-helper-1 response for clearing H1N1 influenza A virus infection." (PMID 38108455, 2023). "Meanwhile, compared to the H1N1 virus infection group, we also found that H1N1 virus-infected mice with RosA treatment had lower levels of CD8+ (green) T cells and the expression of cytotoxic effectors Granzyme B (pink) and TNF-α (red) in the lung tissues." (PMID 37891648, 2023). "The clinical respiratory signs and lung pathology in swine influenza-infected pigs are commonly induced by the pro-inflammatory cytokines such as IFN-α, TNF-α, IL-1 α and β, and IL-6 in bronchoalveolar lavage fluids and the amount of viral load in the lung tissue." (PMID 19317918, 2009).
keratitis (20 papers, 2012 to 2025). A corneal disease that is characterized by inflammation of the cornea. "In vivo, CRAMP−/− mice show increased susceptibility to Pseudomonas aeruginosa (PA) keratitis and enhanced secretion of pro-inflammatory cytokines, including IL-1β, IL-6 and TNF, in PA-infected corneas." (PMID 33468624, 2021). "Reinforcing the importance of TNF-α in the control of corneal inflammation, the TNF-α antagonists, infliximab, adalimumab, and etanercept have been shown to be effective therapies for RA-associated keratitis." (PMID 22229035, 2012). "For instance, a higher level of the pro-inflammatory cytokine TNF-α was detected in rat models with keratitis, which facilitates inflammatory responses and enhances the activation of NF-κB." (PMID 40353954, 2025). "Several studies validated the contribution of NF-κB to systemic inflammation and keratitis, linking its activation to elevated TNF-α levels and heightened inflammatory responses." (PMID 40353954, 2025). "keratitis, including IL-17 signaling, NF-kappaB signaling, TNF signaling, and cytokine–cytokine receptor interaction, as central to the immune response of the host." (PMID 40521031, 2025). "The impact of PL on the expression of HMGB1, LOX-1, TNF-α, IL-1β, IL-6, IL-10 and ROS in A. fumigatus keratitis was investigated using RT-PCR, ELISA, Western blot, and Reactive oxygen species (ROS) assay." (PMID 38655086, 2024). "Some scholars have found that LXA4 attenuates the inflammatory response by downregulating the production of the proinflammatory factors IL-1β, TNF-α, and IL-6 via the Fpr2 receptor in Aspergillus fumigatus keratitis mouse models." (PMID 36544058, 2023). "The ocular response against infectious keratitis induces the secretion of several inflammatory cytokines, such as IL-1a, IL-1β, IL-6, IL-8, tumor necrosis factor α, and the infiltration of immune cells at the site of infection." (PMID 34436544, 2021). "TNF-α is reportedly elevated in corneas from individuals suffering keratitis, and this cytokine has been shown to stimulate MMP-9 activity in HCE cells." (PMID 31003493, 2019). "All the mice suffered keratitis, severe corneal opacity and ELISA results indicated HE4 overexpression, and significantly increased IL-6 and TNF-α levels in the cornea." (PMID 41883385, 2025). "In the S. aureus keratitis study, treatment with genipin revealed a significant downregulation of IL6, TNFα, and interferon γ (IFNɣ) compared to the vehicle-treated group (p = 0.001 for IL6, p = 0.008 for TNFα, p= 0.025 for IFNɣ)." (PMID 37108070, 2023). "During corneal infections, IL-1β, IL-6, IL-8, and TNFα are important in the initiation of inflammatory signals and both TLR2 and TLR5 mediate microbial clearance and cytokine production during S. aureus and PA keratitis." (PMID 28796783, 2017). "Furthermore, our in vivo and in vitro data indicated that STING decreased the stromal infiltration of immune cells and the production of inflammatory cytokines including IL-1β, IL-6, MIP-2, and TNF-α, suggesting that STING plays an anti-inflammatory function in PA-induced keratitis." (PMID 29922287, 2018).
ocular hypertension (20 papers, 2009 to 2025). Abnormally high intraocular pressure. "The same study also demonstrated that functional blockade of TNF-α with an anti-TNF-α blocking antibody or deletion of the gene encoding TNF-α in a genetically altered mouse model prevented ocular hypertension (OH)-induced oligodendrocyte degeneration and the secondary loss of RGCs." (PMID 23559847, 2013). "Consistently, RGCs spared in ocular hypertensive mice by triple knockout of IL1α, TNFα, and C1q were electrophysiologically functional." (PMID 34199494, 2021). "For example, blocking the proinflammatory cytokine signaling using inhibitors of TNFα or Fas receptor reduced RGC death and axon loss in ocular hypertensive animals." (PMID 34199494, 2021). "Ocular hypertension and the levels of inflammatory cells and proinflammatory cytokine tumor necrosis factor-alpha in the aqueous humor were alleviated with fucoxanthin treatment." (PMID 34356327, 2021). "Following induction of ocular hypertension, IL-1α, TNF-α, and C1q production was initially driven by CD11b+ CD11c+ cells." (PMID 33147455, 2020). "The dominant-negative TNFα inhibitor, XPro1595, which selectively inhibits soluble TNFα, rescued Müller cell and microglia/macrophage activation after induction of ocular hypertension." (PMID 27551275, 2016). "Ocular hypertension (OHT) triggers an inflammatory response characterized by the appearance of activated microglia around the ONH that express TNF-α." (PMID 22802951, 2012). "Tissue immunolabeling supported increased production of this pro-inflammatory cytokine in GFAP-labeled astroglia in ocular hypertensive eyes; however, the ocular hypertension-induced TNF-α immunolabeling was prominently decreased in GFAP-IκKβ retinas compared to ocular hypertensive IκKβf/f controls." (PMID 32859212, 2020). "Thus, GFAP-labeled astroglia survived IκKβ deletion over the 12 weeks of experimental period with ocular hypertension and exhibited decreased inflammatory activity as exemplified by decreased production of pro-inflammatory/pro-apoptotic cytokines, including TNF-α." (PMID 32859212, 2020). "Tumor necrosis factor-alpha (TNF-α) is a pro-inflammatory cytokine that binds to TNF receptor 1 (TNFR1) and 2 (TNFR2), resulting in RGC death after optic nerve crush and ocular hypertension." (PMID 39408817, 2024). "The mRNA expression of IL-1β, TNF-α, Fas, IL-6, leukemia inhibitory factor, and IFN-γ was increased significantly in the retina of ocular hypertensive animals at day 7, post injury." (PMID 33628191, 2021). "The promising attempts were done using the inhibitors of soluble TNFα fraction, achieving alleviation of RGC damage in ocular hypertension model." (PMID 30524222, 2018). "Our results demonstrate this link using a different method to induce ocular hypertension (OHT) and a different species than our earlier study, while for the first time identifying microglia at the optic nerve head (ONH) as the source of TNF-α." (PMID 22802951, 2012). "Furthermore, we have shown that elevated protein expression of TNF-α, IL-1β, and IL-6 were attenuated by SNC-121 treatment in ocular hypertensive animals." (PMID 33628191, 2021). "In support of this observation, analysis of isolated Müller glia samples and the immunolabeling of retinas did not detect a significant decrease in the ocular hypertension-induced TNF-α production of Müller glia in GFAP-IκKβ mice." (PMID 32859212, 2020). "Applying of non-selective anti-TNFα agent (etanercept) suppressed microglial activation and provided optic nerve axons neuroprotection in the rat ocular hypertension model." (PMID 30524222, 2018). "When we similarly analyzed TNF-α titers in isolated samples of retinal Müller glia, no statistically significant decrease was detectable in the ocular hypertension-induced production of TNF-α in GFAP-IκKβ mice compared to ocular hypertensive IκKβf/f controls (P = 0.06)." (PMID 32859212, 2020).
ocular hypertension (continued). "The effect of TNF-α inhibition in maintaining near-normal levels of neurofilament and RGCs in rats with OHT suggests that Etanercept may protect axons and secondarily RGC somata even in the presence of persistent ocular hypertension." (PMID 22802951, 2012). "One possible underlying mechanism of the upregulation of p-AMPK and protection from ocular hypertension is that upregulation of p-AMPK may lead to autophagy activation, because AMPK activator A769662 exerted axonal protection with autophagy activation in TNF-induced optic nerve damage." (PMID 37754233, 2023). "Immunoassays and immunolabeling of retina and optic nerve tissues presented reduced production of various proinflammatory cytokines, including TNFα, in GFAP/cFLIP and GFAP/cFLIPL relative to controls at 12 weeks of ocular hypertension with no detectable alteration in TUNEL." (PMID 38824526, 2024).